MYO18B (myosin XVIIIB)
Description:
May be involved in intracellular trafficking of the muscle cell when in the cytoplasm, whereas entering the nucleus, may be involved in the regulation of muscle specific genes. May play a role in the control of tumor development and progression; restored MYO18B expression in lung cancer cells suppresses anchorage-independent growth.
Synonyms: BK125H2.1; KFS4
Tractability: PROTAC: ubiquitination databases record sites on it.
Gene: Protein-coding gene on chromosome 22 (25,742,144 to 26,031,045, forward strand). Ensembl gene ENSG00000133454.
Subcellular location: Cytoplasm; Nucleus; Cytoplasm, myofibril, sarcomere
Subcellular location (Human Protein Atlas): Centrosome; Nucleoplasm
Gene Ontology:
Molecular function: actin filament binding; ATP binding; cytoskeletal motor activity
Cellular component: centrosome; nucleoplasm; unconventional myosin complex; cytoplasm; myosin filament; myosin II complex; cytoskeleton; filamentous actin; myosin complex; nucleus; sarcomere; Z disc
Genetic constraint (gnomAD): Loss-of-function variants: 192 observed, 237.65 expected, observed/expected ratio (o/e) 0.81, 90% interval 0.72 to 0.91. The upper end of that interval is the gene's LOEUF score, 0.91, which puts it in group 3 of 6, group 1 being the genes least tolerant of losing a copy. Missense variants: 3,157 observed, 3,171.3 expected, observed/expected ratio (o/e) 1, 90% interval 0.97 to 1.02. Synonymous variants: 1,316 observed, 1,259.6 expected, observed/expected ratio (o/e) 1.04, 90% interval 1 to 1.09.
Gene-disease validity (ClinGen):
ClinGen rates the evidence that MYO18B causes each of these diseases.
Klippel-Feil anomaly-myopathy-facial dysmorphism syndrome (autosomal recessive): Definitive.
Homologues: Orthologues: chimpanzee MYO18B (97% identical), macaque MYO18B (95% identical), dog MYO18B (82% identical), pig MYO18B (81% identical), guinea pig MYO18B (79% identical), rabbit MYO18B (78% identical), mouse Myo18b (74% identical), rat Myo18b (73% identical), tropical clawed frog myo18b (46% identical). Paralogues in human: MYO18A (32% identical), MYH7 (17% identical), MYH6 (17% identical), MYH3 (16% identical), MYH8 (16% identical), MYH2 (16% identical), MYH4 (16% identical), MYH1 (16% identical), MYH13 (16% identical), MYH7B (16% identical), MYH15 (15% identical), MYH11 (15% identical), and 32 more.